KRAS (KRas proto-oncogene, GTPase)
Diseases named in the same sentence as KRAS in open-access papers (continued):
Sharing a sentence is not in itself a finding about the gene and the disease.
gastric cancer (continued). "One of the miRNAs dysregulated in PC and targeting KRAS is hsa-miR-885-5p, which has previously been reported as a tumour suppressor in hepatocellular carcinoma by regulating AEG1 and as an inhibitor of invasion and metastasis in gastric cancer by regulating ME1." (PMID 39057123, 2024). "Mouse models with activating mutations in KRAS in gastric epithelial cells but not Helicobacter infections resulted in an increase in AR and HB-EGF secretion, supporting the existence of a RTK/MAPK feed-forward loop in gastric cancer." (PMID 32698506, 2020). "In a study of 62 gastric cancer tissue samples, KRAS mutations were detected in only one (1.6%) sample and MGMT methylation was detected in 13 (21%) samples, and no connection was shown between KRAS mutations and MGMT methylation." (PMID 27643594, 2016). "Conversely, the EGFR/HER-2/KRAS pathway has never been investigated in canine gastric cancer." (PMID 24454858, 2014). "Therefore, we hypothesized that in KRAS mutant gastric cancer cells, the blockade of both PI3K/AKT/mTOR and KRAS/mTOR/STAT pathways using NVP-BKM120 and AG490 would be synergistic." (PMID 22159814, 2012). "In addition, while depletion of mutant KRAS reversed cytotoxicity to BI-2536 and volasertib, co-expression of CCNA2 in this context was sufficient to reintroduce sensitivity, indicating that sensitivity to PLK1 inhibitors in KRAS mutant gastric cancer cells is mediated by CCNA2 upregulation." (PMID 32486290, 2020).
endometrial cancer (142 papers, 2007 to 2026). Primary or metastatic malignant neoplasm involving the endometrium (mucous membrane that lines the endometrial cavity). "Some researchers have utilized ddPCR to detect PIK3CA or KRAS mutations in ctDNA to explore the association between ctDNA and endometrial cancer." (PMID 41602395, 2026). "To date, only three documented cases have reported successful treatment outcomes with these agents in KRAS G12C–mutated endometrial cancer—two with adagrasib and one with sotorasib." (PMID 41355935, 2025). "Understanding the molecular basis of KRAS mutations in endometrial cancer opens up opportunities for targeted therapeutic interventions and the development of novel chemotherapeutics with enhanced efficacy." (PMID 40560289, 2025). "The efficacy of these agents in other KRAS G12C–mutated solid tumors remains under investigation, with limited clinical data available in endometrial cancer." (PMID 41355935, 2025). "A retrospective study of 7870 patients with endometrial cancer identified KRAS mutations in 16% of cases, with G12D and G12V being the most common subtypes." (PMID 41355935, 2025). "Kirsten Rat Sarcoma Viral Oncogene Homolog (KRAS) mutations are the most prevalent in Type 1 endometrial cancer." (PMID 40560289, 2025). "PMP is recognized as a potential precancerous lesion for endometrial carcinoma with mucinous differentiation as it frequently harbors KRAS mutations." (PMID 38539494, 2024). "In AH/EIN, the most commonly mutated genes, including PTEN, CTNNB1, ARID1A, PIK3CA, and KRAS, are also mutated in endometrial carcinoma." (PMID 38539494, 2024). "In KRAS-mutated endometrial cancer the wild-type KRAS allele antagonizes tumorigenesis, whereas wild-type HRAS supports transformation in vitro but not in vivo." (PMID 36607281, 2023). "KRAS mutations are found in 10–30% of well-differentiated endometrial cancers and are known for their role as an early checkpoint in the transition from hyperplasia to cancer and as markers of invasive potential in well-differentiated tumours." (PMID 36797358, 2023). "KRAS mutations were found more frequently in patients with endometrial carcinoma and NSMP than in those with other subtypes." (PMID 36797358, 2023). "The KRAS mutation is reported to exist in 10–30% of the type I estrogen-related endometrial cancer and predicts malignant transition as well as progression to advanced-stage disease." (PMID 35796805, 2022). "Recent studies using the whole-genome sequencing technique found that KRAS mutations exist not only in the endometrial cancer but also in the normal endometrium." (PMID 35796805, 2022). "Nevertheless, KRAS mutations seem to be directly associated with type I estrogen-related endometrial cancer and its frequency is estimated to be 10–30%." (PMID 33801965, 2021). "In KRAS-mutated endometrial cancer cells, individual deletion of WT HRAS or NRAS limited proliferation in cancer cells, but not xenograft tumor growth." (PMID 33924994, 2021). "Deletion of WT HRAS lead to decreased proliferation and increased apoptosis in KRAS-mutated endometrial cancer cells." (PMID 33924994, 2021). "First, mutations in PIK3CA and KRAS cause the aberrant activation of downstream signaling pathways, contributing to tumorigenesis and disease progression in endometrial cancer." (PMID 34439385, 2021). "Several studies reported the relations between NRF2 activation and PI3K pathway activation in endometrial carcinoma, or KRAS mutations in other tumor types." (PMID 30908539, 2019). "We found that, in agreement with previous studies, mutations in multiple members of the PI3K pathway and KRAS were co-existed in several endometrial cancer cell lines, including concomitant mutations in the PI3K pathway." (PMID 29426295, 2018).
endometrial cancer (continued). "In terms of the RAS/MAPK pathway, we found activating KRAS mutations in approximately 20% of endometrial cancers." (PMID 29426295, 2018). "The expression of miRNA-324-3p was down-regulated in patients with KRAS-variant endometrial tumors, and miRNA-324-3p was suggested as a prognostic biomarker of endometrial cancer." (PMID 27677182, 2016). "The prevalence of tumor-acquired KRAS mutations has been variably associated with stage, grade and survival in endometrial cancer." (PMID 24732316, 2014). "In the case-control study, to evaluate the role of the KRAS-variant in predicting uterine cancer risk, allele data was obtained for 583 population controls, 430 patients with type 1 endometrial cancer and 37 patients with type 2 cancer." (PMID 24732316, 2014). "Prevalence of KRAS-variant in a control population and in patients with types 1 and 2 endometrial cancer." (PMID 24732316, 2014). "Tumor acquired mutations in KRAS have been identified in 15–30% of type 1 endometrial cancers but are rarely observed (0–5%) in type 2 cancers." (PMID 24732316, 2014). "From other studies using different techniques, it is known that KRAS is mutated in 15–20% of all endometrial cancers." (PMID 24671188, 2014). "This study represents the first analysis of the association of the KRAS-variant with endometrial cancer." (PMID 24732316, 2014). "The association of the KRAS-variant with endometrial cancer risk was evaluated by case-control analysis of 467 women with type 1 or 2 endometrial cancer and 582 age-matched controls." (PMID 24732316, 2014). "The fact that FGFR2 and KRAS mutations are mutually exclusive in endometrial cancers points to the importance of activation of the ERK pathway." (PMID 23941783, 2013). "KRAS mutations were found in 17.9% of the cases, with high frequency of point mutations in exon 2 (G12A, G12C, G12D and G13D), validated in 264 endometrial cancer patients (14,7%;) and also in line with previous studies (18%;)." (PMID 23300780, 2012). "We then examined the correlation of these expression patterns and the mutation status of PTEN, PIK3CA and KRAS, on the basis of our previous data of the frequency of such mutations in an overlapped population of endometrial cancers." (PMID 20664599, 2010). "While coincident mutations in these genes have previously been reported in cancers of the large intestine, PIK3CA and KRAS mutations have typically exhibited a mutually exclusive pattern of occurrence in endometrial cancer." (PMID 19924296, 2009). "KRAS mutations have also been reported in endometrial cancer, suggesting that the results of this study may closely interact with KRAS signaling." (PMID 40805250, 2025). "Screening for KRAS mutations in endometrial cancers may assist in identifying patients at high risk of aggressive disease progression." (PMID 40072110, 2025). "Similarly, KRAS mutations, particularly the c.35G>T (p.Gly12Val) variant, have been recognized in a variety of cancers, including endometrial cancer, where they play a significant role in oncogenic signaling." (PMID 39296440, 2024). "Interestingly, Forkhead box P1 (FOXP1) is known to cause estrogen-dependent endometrial cancers through the KRAS pathway." (PMID 36498516, 2022). "Interestingly, a small number of mutations in canonical endometrial cancer drivers (e.g., KRAS) were identified in this study of adenosarcomas." (PMID 35798968, 2022). "The co-occurrence of MET and PIK3CA or KRAS mutations might also mediate the resistance to c-MET inhibitors when targeting the MET mutation in endometrial cancer." (PMID 34439385, 2021). "Mutations in PIK3CA, PIK3R1, and KRAS also occur at high frequency in endometrial carcinoma." (PMID 34831139, 2021).
endometrial cancer (continued). "KRAS mutations are known to be present in endometrial cancer." (PMID 32066633, 2020). "PTEN and KRAS mutations in endometrial carcinoma may trigger the PI3K/AKT and mitogen-activated protein kinase/extracellular signal-activated kinase (MAPK/ERK) pathway." (PMID 30935077, 2019). "A patient with endometrial cancer and a KRAS mutation also had a PR." (PMID 28008141, 2017). "For example, in our series of endometrial cancer, a KRAS mutation rate of 17% was detected." (PMID 24671188, 2014). "In addition, in two prospective RTOG endometrial cancer trials, miRNA signatures as well as the KRAS-variant were associated with distinct clinical features." (PMID 24732316, 2014). "KRAS mutations have also been detected in endometrial hyperplasia, and may represent an early event in tumorigenesis for type 1 endometrial cancers." (PMID 24732316, 2014). "Furthermore, KRAS mutation was reported to mediate initiation and promotion of endometrial cancer through inducing NF-κB activation." (PMID 23227270, 2012). "The MET/PIK3CA and MET/KRAS co-mutation may have biological impacts on endometrial cancer cells." (PMID 34439385, 2021). "The potential targets for targeted treatment of endometrial cancer (KRAS, PIK3CA, MLH1, MSH6, POLE, PTEN) showed more significant changes in the supernatant of vaginal lavage fluid." (PMID 41602422, 2026). "MEK inhibitors, including trametinib and selumetinib, have shown efficacy in other KRAS-mutant cancers and are currently being investigated for their potential use in endometrial cancers." (PMID 40072110, 2025). "ADMET analysis of 5-fluorouracil makes it a suitable candidate for treating Type 1 endometrial cancer as it is unable to cross the BBB and have better efficacy with the mutated proteins of KRAS gene compared to ifosfamide." (PMID 40560289, 2025). "Of note, mutations in the KRAS, NRAS, and BRAF genes have also been reported in other human malignancies, e.g., colorectal and endometrial cancers." (PMID 39456660, 2024). "KRAS, another member of the RAS oncogene family, was found to be upregulated in SKOV-3 cells and in metastatic lesions in endometrial cancer, which is associated with adverse prognosis." (PMID 39349928, 2024). "Whereas in the group of patients with recurrence, higher levels of KRAS, pATR and pCHEK1 were observed in G1-G2 endometrial carcinomas with statistically significant differences noted for pATR." (PMID 38669256, 2024). "At the same time, individual values of KRAS, pATR and pCHEK1 protein levels in endometrial carcinomas varied significantly ranging from 0 to 78.9%, 1.8 to 58.6% and 3.6 to 78.3%, respectively." (PMID 38669256, 2024). "Significantly elevated levels of KRAS, pATR and pCHEK1 proteins were found in endometrial carcinomas with aneuploidy compared to diploid tumors (p < 0.05)." (PMID 38669256, 2024). "Increased expression of the KRAS oncogene is identified in 22–43% of endometrial carcinomas and leads to changes in the expression of ATR and CHEK1 genes, key components of the ATR-CHEK1-WEE1 signaling pathway responsible for DNA replication and repair." (PMID 38669256, 2024). "In contrast, in patients with recurrence, higher protein levels of KRAS, pATR and pCHEK1 were observed in samples of G1-2 endometrial carcinomas, with statistically significant differences confirmed for pATR." (PMID 38669256, 2024).
endometrial cancer (continued). "The levels of the KRAS oncoprotein were higher in both groups of endometrial carcinomas compared to the level of pATR and pCHEK1 proteins." (PMID 38669256, 2024). "Of the common cancer-associated genes, several genes such as PIK3CA, KRAS, FBWX7, and PPP2R1A are frequently mutated in uterine normal endometrium, which is the origin of both endometriosis and endometrial cancer." (PMID 38067342, 2023). "The TCGA analysis of endometrial cancers has showed that many of these ancestral genes (PTEN, PIK3CA, KRAS, ARID1A, or CTNNB) are frequently mutated (26–80%) indicating that they are likely drivers of oncogenesis." (PMID 36299398, 2022). "Gene mutations in PIK3CA, PIK3R1, KRAS, PTEN, and PPP2R1A commonly detected in type I endometrial cancer cause high activation of the PI3K/Akt/mTOR pathway." (PMID 34831139, 2021). "At the molecular level, type I endometrial cancer is associated with mutations in genes such as PTEN, KRAS, ARID1A, PIK3CA, and CTNNB1 and microsatellite instability (MSI)." (PMID 34565373, 2021). "Taken together, MET mutations highly influence the clinical outcome of advanced endometrial cancer, and KDR and KRAS mutations exhibit additional impacts on patients with a MET mutation." (PMID 34439385, 2021). "Gene mutations in PIK3CA, PIK3R1, KRAS, PTEN, and PPP2R1A commonly detected in type I endometrial cancer lead to PI3K/Akt/mTOR pathway activation." (PMID 34831139, 2021). "First, the MET mutation was noted in 30% of advanced endometrial cancer cases and was associated with a poor clinical outcome; concurrent MET and KRAS mutations indicated the worst outcome." (PMID 34439385, 2021). "Most endometrial cancer cell lines have one or more mutations and/or copy number alterations in the PIK3CA, PTEN, and KRAS genes." (PMID 34831139, 2021). "Fendiline significantly abrogates signaling transduction downstream of the constitutively active KRAS and subsequently blocks proliferation of pancreatic, colon, lung, and endometrial cancer cell lines expressing an oncogenic mutant KRAS." (PMID 34947990, 2021). "In this study, we uncover for the first time the association of the KRAS A59T mutation with MSI-H/dMMR in CRC as well as in other cancer types, including endometrial cancer and gastroesophageal cancer." (PMID 34063999, 2021). "Here, we mainly review the advance of molecular classification and the role of KRAS in endometrial cancer, as well as their correlation with fertility-preservation treatment." (PMID 34975345, 2021). "An intermediate group with prevalent mutations on both pathways would include endometrial carcinoma (PIK3CA 57%, KRAS 21%), colorectal adenocarcinoma (PIK3CA 31%, KRAS 51%), or gastric adenocarcinoma (PIK3CA 24%, KRAS 16%)." (PMID 28532501, 2017).